CASP8 (caspase 8)
Diseases named in the same sentence as CASP8 in open-access papers (continued):
Sharing a sentence is not in itself a finding about the gene and the disease.
brain trauma (3 papers, 2011 to 2022). "A significant increase in total caspase-8 and caspase-9 levels (p < 0.001) corresponding with activation of the selected apoptotic factors within the first 7 days after brain trauma was observed." (PMID 35665033, 2022). "The increase in the Bcl-2/Bax ratio and decrease in caspase-8 and −9 levels demonstrated that pre-treatment with SHJKSmex resulted in anti-apoptotic effects in mice with ischaemic brain injury." (PMID 34184969, 2021). "Neuron-specific deletion of caspase 8 reduces brain damage and improves post-traumatic functional outcomes, suggesting an important role for this caspase in pathophysiology of acute brain trauma." (PMID 21957448, 2011). "In this study, we provide evidence that neuron-specific deletion of caspase 8 reduces brain damage and improves functional outcomes induced by CCI in mice, suggesting an important role for this caspase in the pathophysiology of brain trauma." (PMID 21957448, 2011).
brain tumour (3 papers, 2003 to 2022). "The activation of caspase-8 has been reported in apoptosis induced by betulinic acid in brain-tumour cells.Induction of apoptosis by CDDO or CDDO-Im has been described as being mediated by the activation of DR4, DR5 and caspase-8." (PMID 26751572, 2016).
cervical adenocarcinoma (3 papers, 2012 to 2024). An adenocarcinoma arising from the cervical epithelium. "Data from this in vitro study supports the concept that ESE-15-ol induced apoptosis in cervical adenocarcinoma (HeLa) cells in response to an increase in the G2M block accompanied with increased caspase 8 activity demonstrating the induction of the apoptotic pathway." (PMID 27806731, 2016).
chronic endometritis (3 papers, 2017 to 2024). A non-granulomatous or granulomatous chronic inflammation of the endometrium. "For instance, chronic endometritis is characterized by a modified gene expression profile involving proinflammatory mediators like IL11, IL17, TGF-β, CCL4, IGFBP1, and CASP8, contrasting with the gene expression profile observed in normal fertile women during the implantation window." (PMID 38927030, 2024). "Also, the mechanism of control over the rate of gene transcription or transcriptional regulation is altered in genes involved in chronic endometritis and the inflammatory response (IL-11, CCL4), growth factors (IGFBP1), and apoptotic proteins (BCL2, BAX, CASP8) in infertile patients." (PMID 33329514, 2020).
colon adenocarcinoma (3 papers, 2021 to 2024).
diabetic nephropathy (3 papers, 2011 to 2022). "A. manihot prevents podocyte apoptosis in streptozotocin-induced (STZ) diabetic nephropathy (DN) by inhibiting caspase-3 and caspase-8 expressions." (PMID 36052125, 2022). "In a rat model of diabetic nephropathy, TEA ameliorated podocyte apoptosis by inhibiting the expression of caspase-3 and caspase-8." (PMID 36052125, 2022). "Therefore, to investigate whether the activation of TNFα related caspase 8 and t-Bid (cleaved form of Bid) has any role in STZ-induced diabetic nephropathy and whether mangiferin can inhibit these activations; immunoblot analysis has been carried out using appropriate antibodies." (PMID 25233093, 2014).
diffuse large B-cell lymphoma (3 papers, 2016 to 2022). "The protein expression of caspase-8 (which is inhibited by TNFAIP8) was analyzed by immunohistochemistry in a series of 97 cases of diffuse large B-cell lymphoma, and high expression correlated with a favorable overall and progression-free survival." (PMID 36358737, 2022). "STAT3 also induces chemoresistance in diffuse large B-cell lymphomas through a decreased expression of Casp8, among many other genes." (PMID 33557010, 2021).
experimental autoimmune encephalomyelitis (3 papers, 2020 to 2023). An autoimmune demyelinating disease of the central nervous system that is produced experimentally in animals by the injection of homogenized brain or spinal cord in Freund's adjuvant. "Microglial caspase-8-dependent inflammasome activation has been found to exacerbate neural inflammation in experimental autoimmune encephalomyelitis." (PMID 37684694, 2023). "The Gsta4 effect on apoptosis during adult OL differentiation was corroborated in vivo in both lysolecithin-induced demyelination and experimental autoimmune encephalomyelitis models, where Casp8 activity was reduced in Gsta4-overexpressing OLs." (PMID 32792491, 2020). "During experimental autoimmune encephalomyelitis (EAE) pathogenesis, LPS-induced IL-1β processing in microglia is mediated by caspase-8 through the formation of Interleukin-1 receptor-associated kinase (IRAKM)-caspase-8-ASC complex." (PMID 33805003, 2021).
gallbladder cancer (3 papers, 2021 to 2023). "TRAIL has been previously identified as important markers in gallbladder cancer survival, TRAIL and TNF-α are cytokines that bind to death receptors and recruit CASP-8 which triggers cell death inducing apoptosis in cancer cells." (PMID 33574564, 2021).
hyperuricemia (3 papers, 2018 to 2021). An abnormally high level of uric acid. "Expression of NLRP3 and ASC-speck protein was significantly increased in PPMS, SMS, and AMS patients, but IL-18 and caspase-8 production was significantly increased only in PPMS, in whom a direct correlation between hyperuricemia and caspase-8 was detected." (PMID 29780394, 2018). "Results showed that in PPMS, i.e., in those patients in whom hyperuricemia was detected, a significant positive correlation between serum uric acid concentration and active caspase-8 protein is present (Rsp = 0.811, p < 0.01)." (PMID 29780394, 2018). "Taken together, these results support the hypothesis of hyperuricemia as a common detrimental condition that characterizes MS via the activation of the NLRP3/caspase-8 inflammasome pathway." (PMID 33670164, 2021). "The core targets of plantain for hyperuricemia are RELA, MAPK1, NFKBIA, CASP3, CASP8, and TNF, and the main pathways are pathways in cancer, apoptosis, hepatitis B, IL-17 signaling pathway, and toxoplasmosis." (PMID 33149752, 2020). "There are 31 intersection targets for hyperuricemia, the main targets are RELA, MAPK1, NFKBIA, CASP3, CASP8, and TNF, and the main pathways include pathways in cancer, apoptosis, hepatitis B, IL-17 signaling pathway, and toxoplasmosis." (PMID 33149752, 2020). "The NLRP3/caspase-8 inflammasome pathway is activated in PPMS, possibly as a consequence of hyperuricemia." (PMID 29780394, 2018).
insulinoma (3 papers, 2017 to 2022). "Furthermore, the knockdown of MEN1 was responsible for the down-regulation of caspase 8 activity in human insulinoma cells and human pancreatic stellate cells." (PMID 34878630, 2022). "In a rat insulinoma cell line such as the INS-1O, for example, overexpression of AT2R induces caspase-8, caspase-9, and caspase-3 cleavage and decreases Bcl-2, pAkt, and pERK expression levels." (PMID 28599664, 2017).
leprosy (3 papers, 2015 to 2023). Leprosy is a chronic infectious disease affecting primarily the skin and peripheral nervous system. "The NFKβ1, CASP8, PAR1 and IL4 INDELs were associated with leprosy susceptibility, while NFKβ1, CASP8, PAR1 and CYP19A1 were associated with the MB (Multibacilary) clinical form of leprosy." (PMID 26367014, 2015). "NFKβ1 [rs28362491], CASP8 [rs3834129], PAR1 [rs11267092] and IL4 [rs79071878] genes are potential markers for susceptibility to leprosy development, while the INDELs in NFKβ1, CASP8, PAR1 and CYP19A1 (rs11575899) are potential markers for the severe clinical form MB." (PMID 26367014, 2015). "Several miRNAs that target Caspase-8 (CASP-8) inductor are upregulated in the two leprosy extreme poles." (PMID 38116294, 2023). "The CASP8 showed significant differences associated with the presence of the DEL/DEL homozygous genotype and was associated with a risk factor for leprosy development (p = 0.017; OR[IC95%] = 2.33[1.16–4.69])." (PMID 26367014, 2015). "In conclusion, our study shows that the NFKβ1 [rs28362491], CASP8 [rs3834129], PAR1 [rs11267092] and IL4 [rs79071878] genes are possible markers for the susceptibility to development of leprosy and the severe clinical form MB." (PMID 26367014, 2015). "Taken together, concerning miRNA regulation, our data suggest an antiapoptotic profile for leprosy in general, driven by BCL2, MCL1, and CASP8." (PMID 29593724, 2018). "We investigated the possible effects of CYP19A1 [rs11575899], NFKβ1 [rs28362491], IL1α [rs3783553], CASP8 [rs3834129], UGT1A1 [rs8175347], PAR1 [rs11267092], CYP2E1 [INDEL 96pb] and IL4 [rs79071878] genes in a group of 141 leprosy patients and 180 healthy individuals." (PMID 26367014, 2015).
leukoplakia (3 papers, 2020 to 2023). A white patch or plaque on a mucous membrane that cannot be characterized clinically or pathologically as any other disease. "So, we attempted to find out mutations at one of the driver genes, CASP8, in cancer and adjacent leukoplakia tissues." (PMID 32492030, 2020). "Presence of mutation in CASP8 in both of cancer and adjacent leukoplakia tissues from same patient (n = 8)." (PMID 32492030, 2020). "In total, 56% (15 out of 27) cancer and 30% (8 out of 27) leukoplakia tissues had CASP8 somatic mutations." (PMID 32492030, 2020). "Mutated allele frequencies at CASP8 were found to be more in cancer compared to adjacent leukoplakia tissues." (PMID 32492030, 2020). "Among the 15 patients, 8 had identical CASP8 mutations in both tumor and leukoplakia lesions (located within 2–5 cm of cancer tissue)." (PMID 32492030, 2020). "At 100x sequencing depth, mutations in CASP8 were identified in 56% of tumor (i.e. 15/27) and 30% of leukoplakia (i.e. 8/27) tissues." (PMID 32492030, 2020). "Moreover, an increased frequency of CASP8 mutations has been reported in oral tumor tissues as compared to preneoplastic lesions such as leukoplakia." (PMID 36768994, 2023). "CASP8 mutations have been found increasingly in oral tumor tissues compared to leukoplakia." (PMID 34136393, 2021). "In support of this, we hypothesize, that CASP8 mutations in these leukoplakia tissues, may be an early event followed by mutations in other driver genes which help in progression to malignant transformation." (PMID 32492030, 2020). "This suggests that cells with CASP8 mutations might have gained selective advantage during progression from leukoplakia to tumor." (PMID 32492030, 2020). "For these tumors, it may be interpreted that CASP8 mutation occurred in an early stage of the lesion, i.e. in a leukoplakia patch, where few cells acquired more mutations in other genes and were transformed into cancer." (PMID 32492030, 2020). "We hypothesized that these cancers and leukoplakia tissues might have grown independently from normal epithelium cells and the tumor acquired CASP8 mutations during progression." (PMID 32492030, 2020). "It is interesting to note that four other tumors had CASP8 mutations but the leukoplakias (located at >5 cm away from tumor tissues) did not have mutation." (PMID 32492030, 2020). "Presence of mutation in CASP8 in cancer but not in adjacent leukoplakia tissues from same patients (n = 7)." (PMID 32492030, 2020). "Remaining 7 patients had somatic mutation in CASP8 in tumor but not in its adjacent leukoplakia tissues (located either within 2–5 cm or beyond 5 cm of cancer tissues)." (PMID 32492030, 2020). "Based on the results, we inferred that some molecular changes such as CASP8 mutations may not always get reflected in the histopathological features which are regarded as basis for grading the dysplastic nature of leukoplakia." (PMID 32492030, 2020).
lymphoid leukaemia (3 papers, 2014 to 2022). "Accordingly to these authors, RSV induced a Fas-independent and Caspase-8 (Casp-8) independent apoptosis in the T-cell derived lymphocytic leukemia cell line CEM-C7H2." (PMID 24658441, 2014). "In contrast, emodin and rhein when used with cisplatin or cyclophosphamide only increased in caspase 9 activity in lymphoid leukaemia cells (P ≤ 0.05); whereas cis-stilbene combined with cisplatin increased in caspase 8 and 9 activity, but only in lymphoid leukaemia cell lines (P ≤ 0.05)." (PMID 31360305, 2019).
mesothelioma (3 papers, 2015 to 2025). A usually malignant and aggressive neoplasm of the mesothelium which is often associated with exposure to asbestos. "Silencing EphB2 in mesothelioma cell lines resulted in a pronounced reduction in downstream effectors including matrix metalloproteinase-2 and vascular endothelial growth factor, while the expression of pro-apoptotic mediators such as caspase-8 was upregulated." (PMID 40943224, 2025). "The same effects on MEDI3039 sensitivity were detected in analogous TNFRSF10B, FADD, CASP8, and BID cRNA KO models derived from two additional rTRAlL-sensitive mesothelioma cell lines H2804 and NCI-H28." (PMID 35086954, 2022). "More recent studies also show that SAHA-induced apoptosis is FLIP/caspase 8-dependent and HR23B-independent in mesothelioma." (PMID 25888633, 2015). "To validate the most significant genes identified across both models as conferring resistance to rTRAIL, we used synthetic crRNA to knock out expression of FADD, BID, CASP8, and TNFRSF10B (TRAIL-R2) in the rTRAIL-sensitive MSTO-211H mesothelioma cell line stably expressing Cas9." (PMID 35086954, 2022).
nasopharyngeal carcinoma (3 papers, 2012 to 2020). A carcinoma arising from the nasopharyngeal epithelium. "This type-II RIP has been reported to induce apoptosis by activation of both caspase-8 and caspase-9 regulated pathways in nasopharyngeal carcinoma cells." (PMID 22957017, 2012). "It has also been shown that AE can induce apoptosis in nasopharyngeal carcinoma cell lines (NPC-TW 039 and NPC-TW 076 cells) by regulating caspase activities, including caspase-3, caspase-8, and caspase-9." (PMID 32190086, 2020). "This hypericin-PDT mediated CASP8 activation has been reported in both Jurkat T-lymphocytes and nasopharyngeal carcinoma cells, but not in a variety of murine and human cancer cell lines." (PMID 25076130, 2014).
ovarian serous adenocarcinoma (3 papers, 2021 to 2023). An adenocarcinoma that arises from the ovary and is characterized by the presence of malignant epithelial cells that, in well differentiated tumors, resemble the epithelium of the fallopian tube or, in poorly differentiated tumors, show anaplastic features and marked nuclear atypia. "To verify IPA’s prediction of the nuclear presence of Caspase-8, we separated the lysates of HeLa, SiHa, and two High-Grade Serous Ovarian Cancer (HGSOC) cell lines—OVCAR-3 and OVCAR-8, into their cytosol and nuclear fractions." (PMID 36399280, 2022). "High-Grade Serous Ovarian Cancer (HGSOC) cells lacking Caspase-8 expression showed an altered composition of the RNA Polymerase II-containing transcriptional elongation complex leading to increased transcriptional activity." (PMID 38201534, 2023).
pemphigus (3 papers, 2018 to 2024). Pemphigus is a group of rare autoimmune diseases that cause blistering of the skin and mucous membranes (mouth, nose, throat, eyes, and genitals).This conditioncan occur at any age, but often strikes people in middle or older age. "Several reports investigated the relevance of the FAS pathway in human pemphigus blister formation; upregulation of FAS ligand after pemphigus autoantibody binding induces keratinocyte apoptosis and desmoglein cleavage through the activation of caspase-8." (PMID 38393106, 2024). "In particular, cleaved caspase-8 and -3 are detected in keratinocytes of pemphigus lesions, and caspase-8-positive keratinocytes display increased Fas Ligand expression." (PMID 37503332, 2023). "Since PVIgG have been shown to induce the co-aggregation of FasL and Fas receptor with caspase-8 in death–inducing-signaling complex, we first analyzed the expression of Fas in pemphigus skin." (PMID 29535737, 2018). "In particular, cleaved caspase-8 and -3 are detected in pemphigus lesions, and caspase-8-positive cells express Fas ligand (FasL)/Fas binding." (PMID 29535737, 2018). "The data presented here strongly indicate sFasL activation of caspase-8 and subsequent activation of caspase-3 as the main mechanism accounting for Dsg cleavage and blister formation in pemphigus." (PMID 29535737, 2018). "We have shown previously that anti-FasL antibodies (Ab) prevent PVIgG-induced caspase-8 activation and Dsg cleavage in human keratinocytes and that sera from pemphigus patients contain abnormally increased levels of FasL." (PMID 29535737, 2018). "We have shown previously that anti-Fas ligand (FasL) antibody (Ab) prevents PVIgG-induced caspase-8 activation and Dsg cleavage in human keratinocytes, and that sera from pemphigus patients contain abnormally increased levels of FasL." (PMID 29535737, 2018). "Anti-FasL antibodies (Ab) prevent PVIgG-induced caspase-8 activation and DSG cleavage in human keratinocytes in vitro as well as blister formation in an in vivo mouse model of pemphigus." (PMID 37503332, 2023).
primary immunodeficiency (3 papers, 2016 to 2023). "Germline mutations in human caspase-8 or its key adapter FADD cause a primary immunodeficiency associated with severe recurrent bacterial infections, encephalopathy and hepatopathy." (PMID 27737018, 2016). "Spontaneous mutations in human caspase-8 that render it catalytically inactive are linked with primary immunodeficiency and recurrent sinopulmonary and mucocutaneous infections." (PMID 27737018, 2016).
prostate adenocarcinoma (3 papers, 2013 to 2021). "Caspase-8 mRNA was significantly upregulated in primary prostate adenocarcinoma, compared to normal prostate tissue (P < 0.01)." (PMID 34482382, 2021). "A study with human prostate adenocarcinoma cells (DU145) demonstrated that cranberry extract increases Par-4 expression, which in turn activates caspase-8, leading to increased cleavage of Bid protein with consequent induction of apoptosis." (PMID 23760770, 2013).
sarcopenia (3 papers, 2023 to 2025). Progressive decline in muscle mass due to aging which results in decreased functional capacity of muscles. "Our work reveals a novel mechanism that TNF-ɑ/caspase-8/caspase-3/GSDME signaling-mediated pyroptosis contributes to the development of sarcopenia." (PMID 36823174, 2023). "Our study highlights the pathophysiological role of pyroptosis mediated by TNF-ɑ/caspase-8/caspae-3/GSDME signaling in the development of sarcopenia." (PMID 36823174, 2023). "Evidence of GSDME-mediated pyroptosis and activation of apoptotic caspase-8/-3 were also found in skeletal muscle cells of aged mice with sarcopenia." (PMID 36823174, 2023). "An animal study using the sarcopenic mice model found that TNF-α contributed to sarcopenia by mediating pyroptosis, one type of programmed cell death, through activating the pathways of caspase-8 and caspase-3." (PMID 38032288, 2023). "Notably, melatonin preserves mitochondrial structural and functional integrity, attenuating age-associated myofiber atrophy and counteracting LPS-induced apoptosis via the TNFRSF12A/caspase-8 axis in sarcopenia models." (PMID 40563280, 2025). "In the current study, we identified that aged mice with sarcopenia presented a chronic low-grade inflammation with a high level of serum TNF-α and local TNF-α overexpression in GM, accompanied by evidence of GSDME-mediated pyroptosis and activation of apoptotic caspase-8/-3 in skeletal muscle cells." (PMID 36823174, 2023).